IFITM1 (interferon induced transmembrane protein 1)
Diseases named in the same sentence as IFITM1 in open-access papers (continued):
Sharing a sentence is not in itself a finding about the gene and the disease.
pancreatic cancer (5 papers, 2021 to 2023). "Hence, it is very likely that IFITM1 may also hold hitherto undiscovered value in pancreatic cancer and might be further associated with prognosis of patients with pancreatic cancer." (PMID 33869009, 2021). "Although we discovered the potential role of IFITM1 in pancreatic cancer, limitations to this study were acknowledged." (PMID 33869009, 2021). "As we discovered above, immune cell infiltration was in significant correlation with IFITM1 in pancreatic cancer." (PMID 33869009, 2021). "It was confirmed that IFITM1 played a vital role in pancreatic cancer by analyzing the clinical and pathological characteristics of 90 patients with pancreatic cancer and their survival rate as well as by verifying through several bioinformatics online tools." (PMID 33869009, 2021). "Univariable and multivariable Cox regression analyses for overall survival, accounting for IFITM1 expression and clinicopathological features in 90 patients with pancreatic cancer." (PMID 33869009, 2021). "Based on the data from the Oncomine database, the transcriptional level of IFITM1 was significantly elevated in pancreatic cancer tissue vs. normal pancreatic tissue." (PMID 33869009, 2021). "Eight studies reported from 2003 to 2009 were filtered out with the screening condition of “IFITM1; Cancer vs. Normal Analysis; Cancer Type: Pancreatic Cancer” and assessed with a heat map analysis." (PMID 33869009, 2021). "A significant upregulation of the selected DEG, interferon (IFN)-induced transmembrane protein 1 (IFITM1), was evaluated in several bioinformatics online tools and verified with immunohistochemistry staining from samples of 90 patients with pancreatic cancer." (PMID 33869009, 2021). "Meanwhile, we found the protein expression of IFITM1 with the help of the Human Protein Atlas, and the positively strong level was also found in pancreatic cancer specimens compared with normal tissues." (PMID 33869009, 2021). "First, we used the Oncomine database to explore the transcriptional level of IFITM1 in pancreatic cancer and normal pancreatic tissues." (PMID 33869009, 2021). "Consistent with the outcomes of several bioinformatics online tools, IFITM1 was found highly expressed in pancreatic cancer compared to normal pancreatic tissues and was confirmed through IHC experiment later." (PMID 33869009, 2021). "In the multivariable analysis, IFITM1 expression (HR = 2.134; 95% CI 1.073, 4.245; p = 0.031) remained an independent prognostic marker for OS of patients with pancreatic cancer." (PMID 33869009, 2021). "A total of 184 patients with pancreatic cancer in the TCGA database, with 5 of them having no documented T or N stage, leaving 179 patients for the confirmation of the relationship between IFITM1 and human pancreatic cancer." (PMID 33869009, 2021). "The median OS of the patients with pancreatic cancer with the low and high IFITM1 expression was 43.0 vs. 10.0 months, respectively." (PMID 33869009, 2021). "Immunohistochemical experiments were applied to validate IFITM1 expression in 90 patients with pancreatic cancer." (PMID 33869009, 2021). "Representative IHC-stained images showed that IFITM1 is mainly located in the cell membrane of the pancreatic cancer tissues." (PMID 33869009, 2021). "Relationship between the expression of IFITM1 and clinical characteristics of 90 patients with pancreatic cancer." (PMID 33869009, 2021). "The association of IFITM1 with immunogenicity was also suggested in a pancreatic cancer model, in which upregulated IFITM1 expression levels had protumorigenic functions; however, IFITM1 was positively correlated with the number of tumor-infiltrating immune cells." (PMID 36466909, 2022). "Moreover, the wound-healing assay indicated that IFITM1 silencing inhibited cell migration capability, and the colony-formation assay showed that it greatly reduced the cancer stem cell-like properties of pancreatic cancer." (PMID 33869009, 2021).
pancreatic cancer (continued). "Recently, with great interest we read a study “Identification of IFN-Induced Transmembrane Protein 1 With Prognostic Value in Pancreatic Cancer Using Network Module-Based Analysis” in Frontiers in Oncology, revealing that the expression level of IFITM1 was increased in pancreatic cancer." (PMID 34354954, 2021). "Consistent with our investigation, IFITM1 might be an oncogene for pancreatic cancer that participates in tumorigenesis." (PMID 33869009, 2021). "Moreover, down-regulation of IFITM1 significantly suppressed the tumorigenicity of pancreatic cancer cells." (PMID 34354954, 2021). "Taken together, our study constructed an effective FI network-based module analysis to discover the differentially expressed genes between pancreatic cancer and normal pancreatic tissues and suggested that the upregulation of IFITM1 correlated to a poor clinical result of pancreatic cancer." (PMID 33869009, 2021). "The χ2-test was applied to assess the relationship between the expressions of IFITM1 and the clinical and pathologic features of patients with pancreatic cancer, including gender, age at diagnosis, tumor size, histologic differentiation, TNM stage, nodal status, and distant metastasis." (PMID 33869009, 2021). "Notably, the histologic differentiation (p = 0.032) and TNM stage (p = 0.044) of the patients with pancreatic cancer were significantly correlated with IFITM1 expression in the clinical and pathological analyses." (PMID 33869009, 2021). "Combining the results from the functional analysis of the FI network and literature mining, we were interested to see if IFITM1 could be a potential biomarker in pancreatic cancer." (PMID 33869009, 2021). "Collectively, our findings suggested that IFITM1 might have promising utility for pancreatic cancer." (PMID 33869009, 2021). "Yet, it is still unclear whether IFITM1 is of prime importance in the responsiveness of patients with pancreatic cancer to clinical therapies." (PMID 33869009, 2021). "Three types of pancreatic cancer cell lines and normal human pancreatic duct epithelial cell line HPDE6-C7 were used to examine the expressions of IFITM1." (PMID 33869009, 2021). "Furthermore, a higher level of IFITM1 was assessed in pancreatic cancer cell lines compared to normal human pancreatic duct epithelial cells, and silencing IFITM1 in tumor cells remarkedly inhibited cancer tumorigenicity." (PMID 33869009, 2021).
colon cancer (4 papers, 2016 to 2024). "Recently, IFITM1 was shown to be highly expressed in several cancers, including cervical, esophageal, ovarian, brain, and colon cancer." (PMID 27852071, 2016). "In line with the results obtained by shRNA-mediated knockdown, ectopic expression of IFITM1 increased the proliferation as well as migration ability of colon cancer cells." (PMID 27852071, 2016). "Yu and their colleagues indicated that the IFITM1 could facilitate colon cancer metastasis by regulating CAV-1." (PMID 37063301, 2023).
esophageal adenocarcinoma (4 papers, 2016 to 2024). A malignant tumor with glandular differentiation arising predominantly from Barrett mucosa in the lower third of the esophagus. "The proposed negative impact of IFITM1 on TTR and OS in esophageal adenocarcinoma has to be interpreted with caution since it was only demonstrated in the adjusted Cox regression analysis." (PMID 27186374, 2016). "In esophageal adenocarcinoma expression of IFITM1 had no impact on TTR or OS in Kaplan-Meier-analyses, but in the adjusted Cox regression IFITM1 expression had a negative impact on both TTR (HR 3.05, 95 % CI 1.09-8.53) and OS (HR 2.71, 95 % CI 1.11-6.67)." (PMID 27186374, 2016). "In esophageal adenocarcinoma, expression of IFITM1 had no impact on TTR and OS in the Kaplan-Meier-analyses, but in the adjusted Cox regression analyses) high IFITM1 expression had a negative impact on both TTR (HR 3.05, 95 % CI 1.09-8.53, p = 0.034) and OS (HR 2.71, 95 % CI 1.11-6.67, p = 0.029)." (PMID 27186374, 2016).
esophageal cancer (4 papers, 2016 to 2024). A primary or metastatic malignant neoplasm involving the esophagus. "We found that among various IFITMs, only IFITM1 and IFITM3 were highly expressed in tumor tissues from both colon adenocarcinoma (COAD) and esophageal carcinoma (ESCA) patients as compared to normal tissue." (PMID 38167862, 2024).
gastric tumor (4 papers, 2010 to 2020). "In the subset of gastric tumors there were significant associations of high IFITM1 expression with age and Lauren’s intestinal type, respectively." (PMID 27186374, 2016). "The upregulation of IFITM1 in cancer cells was associated with an increase in migration and invasive capacity, and its action in gastric tumour cells was linked to suppression of NK cells." (PMID 20707927, 2010).
glioblastoma (4 papers, 2018 to 2024). The most malignant astrocytic tumor (WHO grade IV). "Elevated IFITM1 levels were associated with improved survival outcomes in patients with chronic myeloid leukemia and glioblastoma." (PMID 39273214, 2024). "It has been recently reported that in U87 glioblastoma cells IFITM proteins inhibit HIV-1 entry in a co-receptor-dependent manner, that is, IFITM1 is more inhibitory on CCR5 tropic HIV-1 whereas IFITM2/3 confers a greater suppression of CXCR4 counterparts." (PMID 30087232, 2018).
HIV-1 infection (4 papers, 2015 to 2024). The type species of lentivirus and the etiologic agent of acquired immunodeficiency syndrome (AIDS). "On the other hand, HIV-1 infection triggers the over-expression of several RFs genes, including IFITM1, IFITM2, IFITM3, MX1, MX2, TETHERIN, IFN1a, and IFNR." (PMID 39476027, 2024). "Although IFITM1 does not affect the entry of either HIV-1BH10 or HIV-1NL4–3, production of both viruses is diminished in the one-round infection assay, which alludes to inhibition of a post-entry step of HIV-1 infection by IFITM1." (PMID 25738301, 2015). "Indeed, we have observed that FLAG-tagged IFITMs are approximately 25–30% more potent than their WTs to inhibit HIV-1 infection; however, the order of potency in inhibition for the untagged WT IFITMs and FLAG-IFITMs remains the same, that is, IFITM3 > IFITM2 > IFITM1." (PMID 30087232, 2018).
neuroblastoma (4 papers, 2012 to 2022). Neuroblastoma (NB) is the most common solid, extracranial childhood tumor. "The IFITM protein family was first discovered in 1984 by a cDNA screen of IFN-stimulated neuroblastoma cells and currently consists of five members in humans (IFITM1, 2, 3, 5, and 10), of which only IFITM1, 2, and 3 have been identified as potent inhibitors of virus entry." (PMID 35458456, 2022). "The IFITM family (in humans, five IFITM members: IFITM1, IFITM2, IFITM3, IFITM5, and IFITM10; in mice, seven Ifitm members: IFITM1, IFITM2, IFITM3, IFITM5, IFITM6, IFITM7, IFITM10) was first discovered as interferon-induced genes in human neuroblastoma cells." (PMID 36012150, 2022).
squamous cell carcinoma (4 papers, 2012 to 2024). A carcinoma arising from squamous epithelial cells. "Intriguingly, IFITM1 is highly overexpressed in tumor epithelia cells of human squamous cell carcinomas and in adenocarcinomas of NSCLC patients." (PMID 23115618, 2012). "For this study, a cell model that was engineered in our previous publication is used to investigate the role of IFITMs—SiHa cells originating from squamous cell carcinoma of the cervix which express IFITM1 and IFITM3 at detectable endogenous levels with a higher expression upon IFNγ stimulation." (PMID 36008984, 2022). "Interestingly, we found strong IFITM1 overexpression in the tumor epithelia cells of human squamous cell carcinomas as well as in adenocarcinomas of NSCLC patient samples." (PMID 23115618, 2012).
endometrial stromal tumor (3 papers, 2021 to 2026). Neoplasms of the endometrial stroma that sometimes involve the myometrium. "IMT typically expresses smooth muscle markers (desmin, SMA, caldesmon, transgelin) and stromal markers (CD10, IFITM1), which can lead to misdiagnosis as leiomyoma or endometrial stromal tumor." (PMID 41560086, 2026). "The main IHC markers for diagnosing endometrial stromal tumors are CD10 and the more recently introduced marker IFITM1." (PMID 39836188, 2025).
esophageal squamous cell carcinoma (3 papers, 2016 to 2017). Esophageal squamous cell carcinoma (ESCC) is a type of esophageal carcinoma (EC) that can affect any part of the esophagus, but is usually located in the upper or middle third. "In esophageal squamous cell carcinoma (ESCC), IFITM1-depleted cancer cells displayed a high sensitivity to cisplatin treatment." (PMID 27852071, 2016).
metastatic tumors (3 papers, 2013 to 2020). "Subsequently, we performed IFITM1 immunostaining in orthotopic tumors and their corresponding metastatic tumors from mice and found that IFITM1 protein levels were higher in metastatic tumors than in orthotopic tumors." (PMID 32668617, 2020). "Thus, IFITM1 expression is elevated in metastatic tumors compared with that in orthotopic tumors in our orthotopic SCLC metastasis model." (PMID 32668617, 2020). "We examined IFITM1 mRNA expression levels in isolated tumor cells subjected to the DNA microarray analysis by real-time RT-PCR and confirmed that its expression was higher in metastatic tumors than in orthotopic tumors." (PMID 32668617, 2020). "In this study, we compared the gene expression profiles of orthotopic and metastatic tumors in an orthotopic metastasis model using DMS273 cells and identified IFITM1 as a highly upregulated protein in metastatic sites." (PMID 32668617, 2020). "In summary, we identified IFITM1 as a metastasis-promoting factor for SCLC by analyzing differentially expressed genes between orthotopic and metastatic tumors in an SCLC xenograft model." (PMID 32668617, 2020).
atherosclerosis (2 papers, 2025). A disease characterized by the build-up of fatty material and calcium deposition in the arterial wall resulting in partial or complete occlusion of the arterial lumen. "We demonstrated that IFITM1 contributes directly to atherosclerosis by regulating the phenotypic switch of vascular smooth muscle cells (VSMCs)." (PMID 41368318, 2025). "IFITM1 and IFITM3 are two interferon-induced transmembrane proteins that might play significant roles in the pathophysiology of atherosclerosis, particularly through their involvement in inflammation, endothelial function, and vascular health." (PMID 40607379, 2025).
autoimmune disease (2 papers, 2014 to 2022). A disorder resulting from loss of function or tissue destruction of an organ or multiple organs, arising from humoral or cellular immune responses of the individual to their own tissue constituents. "However, the definite mechanism of IFITM1 in autoimmune diseases remains unclear." (PMID 35609018, 2022).
cervical squamous cell carcinoma (2 papers, 2017 to 2019). A squamous cell carcinoma arising from the cervical epithelium. "Several studies have shown the therapeutic potential of IFITM1 regulation in breast and cervical squamous cell carcinoma." (PMID 31888295, 2019). "IFITM1 gene expression may reduce the proliferation, migration, and invasion of cervical squamous cancer cells." (PMID 29051711, 2017). "However, the role of IFITM1 gene in cervical squamous cell cancer is unclear." (PMID 29051711, 2017).
co-infection (2 papers, 2023 to 2025). "An early and enhanced upregulation of IFN-induced antiviral gene expression (indicated by RIG-I, IFN-β-1, Mx1, and IFITM1) was observed in A549 cells for the treatment with DIPs only and the co-infection with RSV in comparison to infection with RSV only." (PMID 37766278, 2023). "Co-expression of IFI6, IFITM1 and IFITM3 across lymphoid tissues may be connected to enhanced pathogenesis in co-infection." (PMID 40211134, 2025).
colitis (2 papers, 2022 to 2023). Inflammation of the colon. "The polymorphisms of IFITM1 increase the sensitivity to ulcerative colitis, and the expression of IFITM1 is also up-regulated in colitis." (PMID 35893911, 2022). "Therefore, the increased levels of PBLD, FAM3D, KRT8, SULT2B1, GPA33, DEPTOR, and decreased expression of ACSL4, IFITM1 and HSD11B1 caused by mEVs has been demonstrated to attenuate colitis, implying that consumption of mEVs has the potential to improve intestinal health." (PMID 35893911, 2022).
dermatitis (2 papers, 2019 to 2024). An inflammatory process affecting the skin. "Among the generated regulatory network, STAT1, IFITM1, ISG15, and MX1 were genes associated with the IFN signaling pathway, while STAT1 and MX1 were associated with dermatitis, and STAT1 and ISG15 were associated with the inflammatory response." (PMID 30634634, 2019).
dry eye (2 papers, 2021 to 2023). "Interferon-gamma can enhance the expression of IFITM1 in the conjunctiva of patients with dry eye syndrome, which may play a role in abnormal terminal differentiation of the epithelium." (PMID 37965330, 2023). "Elevated IFITM1 levels have been reported in the conjunctiva of dry eye patients." (PMID 34349764, 2021).
endometriosis (2 papers, 2021 to 2022). The growth of functional endometrial tissue in anatomic sites outside the uterine body. "Detection of ectopic endometrial epithelial and stromal cells in TE was most often performed with ER, PR, and CD10, but recently interferon-inducible transmembrane protein 1 (IFITM1) for stromal and Pax8 for epithelial cells seem to be also highly sensitive markers for extra-pelvic endometriosis." (PMID 33477657, 2021).
HCMV infection (2 papers, 2019 to 2025). "However, as with infection of MyD88-expressing cells, we observed that the UL88-STOP-mCh HCMV infection, in which MyD88 levels are higher, actually downregulated a number of antiviral ISGs, including IFITM1, IFITM2, IFITM3, MX1, and IFI16 (the nuclear sensor that plays a role in sensing of HCMV)." (PMID 40638072, 2025). "Short hairpin RNA (shRNA) knockdown of IFITM1 alone or in combination with IFITM2 and IFITM3 inhibits HCMV infection as they are required for successful formation of the HCMV virion assembly complex (vAC) and production of infectious progeny virions." (PMID 31921100, 2019). "However, overexpression of IFITM1, IFITM2 and IFITM3 does not inhibit HCMV infection but rather results in a modest increase in the percentage of infected cells." (PMID 31921100, 2019).
inflammatory bowel disease (2 papers, 2022 to 2025). A spectrum of small and large bowel inflammatory diseases of unknown etiology. "Cluster 6 was characterized by the expression of the IFN-γ–induced genes Ifitm1, Ifitm2, and Ifitm3, which have been reported to be associated with inflammatory bowel diseases, alongside with the integrin Itgb1." (PMID 40924026, 2025).
leiomyoma (2 papers, 2021 to 2026). A well-circumscribed benign smooth muscle neoplasm characterized by the presence of spindle cells with cigar-shaped nuclei, interlacing fascicles, and a whorled pattern. "In the two groups of pre- and post-menopausal, the expressions of IFITM1, SMA, and h-caldesmon were significantly different in EST and leiomyomas and showed the same trend." (PMID 34556086, 2021).
multiple myeloma (2 papers, 2023 to 2026). "In this study, we investigate the association between insulin signalling-induced IFITM1 expression and multiple myeloma (MM) aggressiveness." (PMID 42286874, 2026).
myelogenous leukemia (2 papers, 2011 to 2013). "Given that HTX or 293 cells do not express a significant level of endogenous IFITMs, especially IFITM1 and 3, we next used a myelogenous leukemia line, K562 cells, to address if depletion of IFITM expression would enhance viral entry." (PMID 23358889, 2013). "To explore the role of endogenous IFITM1, we used human myelogenous leukemia K562 cells, which express relatively high levels of this IFITM protein." (PMID 21253575, 2011).